CCDC187 (coiled-coil domain containing 187)
Synonyms: MGC50722
Gene: Protein-coding gene on chromosome 9 (136,249,973 to 136,306,901, reverse strand). Ensembl gene ENSG00000260220.
Pathways (Reactome):
Signal Transduction: RHOC GTPase cycle
Gene Ontology:
Molecular function: microtubule binding
Biological process: microtubule anchoring
Cellular component: centrosome
Genetic constraint (gnomAD): Loss-of-function variants: 24 observed, 29.05 expected, observed/expected ratio (o/e) 0.83, 90% interval 0.6 to 1.16. The upper end of that interval is the gene's LOEUF score, 1.16, which puts it in group 5 of 6, group 1 being the genes least tolerant of losing a copy. Missense variants: 661 observed, 841.45 expected, observed/expected ratio (o/e) 0.79, 90% interval 0.74 to 0.84. Synonymous variants: 307 observed, 355.1 expected, observed/expected ratio (o/e) 0.86, 90% interval 0.79 to 0.95.
Homologues: Orthologues: chimpanzee CCDC187 (96% identical), dog CCDC187 (47% identical), mouse Ccdc187 (45% identical), rat Ccdc187 (44% identical), macaque CCDC187 (42% identical).
Diseases named in the same sentence as CCDC187 in open-access papers:
CCDC187 is named in the same sentence as 1 disease in open-access papers, as found by Europe PMC text mining. Sharing a sentence is not in itself a finding about the gene and the disease.
CCDC187 shares sentences with these, for which no sentence is quoted: colorectal cancer (1 paper).